EFNA2 (ephrin A2)
Description:
Cell surface GPI-bound ligand for Eph receptors, a family of receptor tyrosine kinases which are crucial for migration, repulsion and adhesion during neuronal, vascular and epithelial development. Binds promiscuously Eph receptors residing on adjacent cells, leading to contact-dependent bidirectional signaling into neighboring cells. The signaling pathway downstream of the receptor is referred to as forward signaling while the signaling pathway downstream of the ephrin ligand is referred to as reverse signaling. With the EPHA2 receptor may play a role in bone remodeling through regulation of osteoclastogenesis and osteoblastogenesis (By similarity).
Synonyms: LERK-6; HEK7-L; EPLG6; LERK6; ELF-1
Tractability: Antibody: UniProt places it where antibodies can reach, with high confidence; its Gene Ontology location is reachable by antibodies, with high confidence; UniProt predicts a signal peptide or a membrane-spanning region.
Gene: Protein-coding gene on chromosome 19 (1,285,873 to 1,301,431, forward strand). Ensembl gene ENSG00000099617.
Subcellular location: Cell membrane
Subcellular location (Human Protein Atlas): Cytosol; Mitochondria
Pathways (Reactome):
Developmental Biology: EPH-Ephrin signaling; EPH-ephrin mediated repulsion of cells; EPHA-mediated growth cone collapse
Gene Ontology:
Molecular function: protein binding; ephrin receptor binding
Biological process: axon guidance; bone remodeling; cell-cell signaling; ephrin receptor signaling pathway; osteoclast differentiation; cell communication; olfactory bulb development; signaling
Cellular component: plasma membrane; membrane; neuromuscular junction; perikaryon
Genetic constraint (gnomAD): Loss-of-function variants: 17 observed, 17.6 expected, observed/expected ratio (o/e) 0.97, 90% interval 0.66 to 1.45. The synonymous counts are far from expectation, so gnomAD's model fits this gene poorly and the ratio says little. Missense variants: 288 observed, 264.08 expected, observed/expected ratio (o/e) 1.09, 90% interval 0.99 to 1.2. Synonymous variants: 172 observed, 121.54 expected, observed/expected ratio (o/e) 1.42, 90% interval 1.25 to 1.61.
Homologues: Orthologues: macaque EFNA2 (98% identical), dog EFNA2 (96% identical), pig EFNA2 (96% identical), mouse Efna2 (89% identical), rat Efna2 (89% identical), guinea pig EFNA2 (83% identical), chimpanzee EFNA2 (79% identical), tropical clawed frog efna2 (66% identical), zebrafish efna2a (50% identical), zebrafish efna2b (47% identical), Caenorhabditis elegans efn-4 (24% identical), Caenorhabditis elegans efn-2 (23% identical), and 3 more. Paralogues in human: EFNA5 (50% identical), EFNA3 (42% identical), EFNA4 (38% identical), EFNA1 (37% identical), EFNB1 (26% identical), EFNB3 (24% identical), EFNB2 (23% identical).
Diseases named in the same sentence as EFNA2 in open-access papers:
EFNA2 is named in the same sentence as 36 diseases in open-access papers, as found by Europe PMC text mining. Sharing a sentence is not in itself a finding about the gene and the disease. The quoted sentences say what the papers report.
prostate carcinoma (6 papers, 2022 to 2024). A carcinoma that arises from epithelial cells of the prostate gland. "Evidence from a related study suggests that exosomal EFNA2 is a diagnostic biomarker for prostate cancer." (PMID 35945523, 2022). "Ephrin A2 (EPHA2), a tyrosine kinase receptor that is associated with aggressive prostate cancer and adverse prognosis, was detected with 14 biotinylation sites." (PMID 38053024, 2023). "Furthermore, EFNA2 has been found to play an important role in angiogenesis and promoting epithelial-mesenchymal transformation in prostate cancer through in vitro and in vivo migration—and therefore a potential therapeutic target for prostate cancer." (PMID 35309935, 2022). "Literature evidence shows that EFNA2 promotes EMT and increases angiogenesis in prostate cancer." (PMID 35945523, 2022).
gastric cancer (4 papers, 2021 to 2023). A primary or metastatic malignant neoplasm involving the stomach. "While EFNA2 signaling modification has not been evaluated in cutaneous melanoma, upregulation of EFNA2 expression in gastric cancer tissue suggests a potential role in cancer behavior." (PMID 36676129, 2023). "For these reasons, our results suggest that FPR2, CARD14, CXCR2, EFNA2, CXCR1, AQP9 TRIP13, along with GHRL and KLK11, could be used as promising biomarkers for gastric cancer diagnosis or prognostic evaluation." (PMID 34012923, 2021).
glioblastoma (3 papers, 2008 to 2024). The most malignant astrocytic tumor (WHO grade IV). "For example, chimeric antigen receptor T cells simultaneously targeting HER2, IL13Rα2, and ephrin-A2 have been reported to overcome antigenic heterogeneity and lead to improved treatment outcomes in IDH wild-type glioblastoma." (PMID 37944044, 2024).
bladder urothelial carcinoma (2 papers, 2022 to 2023). "The expression of EFNA1 was high in bladder urothelial carcinoma (BLCA), EFNA2 was highest in stomach adenocarcinoma (STAD), and EFNA3 was highest in lung squamous cell carcinoma (LUSC)." (PMID 35309935, 2022).
autism spectrum disorder (1 paper, 2017). A spectrum of developmental disorders that includes autism, and Asperger syndrome. "The disturbance to the architecture of the neocortex observed following deletion of ephrin-A2 signaling shares many similarities with defects found in the neocortex of children diagnosed with autism spectrum disorder." (PMID 28924206, 2017).
breast carcinoma (1 paper, 2024). "In breast cancer, ART increased EPHA8, EPHA10, EFNA2 and reduced EPHA3, EPHA7, and EFNA3." (PMID 38630320, 2024).
colorectal cancer (1 paper, 2016). A primary or metastatic malignant neoplasm that affects the colon or rectum. "Human HCT116 colorectal cancer cells were treated with 0-300 nM NW457 for 24 h or 48 h, respectively, and the expression levels of ephrin A2 (EPHA2) and epidermal growth factor receptor (EGFR) were measured by FACS surface staining." (PMID 27259245, 2016).
endothelial dysfunction (1 paper, 2024). In vascular diseases, endothelial dysfunction is a systemic pathological state of the endothelium (the inner lining of blood vessels) and can be broadly defined as an imbalance between vasodilating and vasoconstricting substances produced by (or acting on) the endothelium. "We also found dysregulation of angiogenesis genes (XDH, SEMA5A, and SULF1) and the Rap1 pathway (ADORA2B, GNAO1, SULF1, and EFNA2), which promotes endothelial homeostasis and may be involved in endothelial dysfunction-associated cardiovascular pathologies." (PMID 38255763, 2024).
glioma (1 paper, 2021). A benign or malignant brain and spinal cord tumor that arises from glial cells (astrocytes, oligodendrocytes, ependymal cells). "SL701 is another newly developed multi-peptide vaccine that targets three peptides that are over overexpressed in gliomas, ephrin A2, survivin, and IL-13 receptor α-2." (PMID 34572775, 2021).
hepatocellular carcinoma (1 paper, 2024). A malignant tumor that arises from hepatocytes. "According to previous reports, PPP2R5B, and EFNA2 can be used as a prognostic biomarker for hepatocellular carcinoma." (PMID 39671369, 2024).
osteosarcoma (1 paper, 2025). A usually aggressive malignant bone-forming mesenchymal neoplasm, predominantly affecting adolescents and young adults. "More recently, enhanced cell proliferation and reduced apoptosis, leading to DR, were comparatively found in several human and canine osteosarcoma cell lines related to the overexpression of ephrin A2 (EphA2) receptor tyrosine kinase." (PMID 40563676, 2025).
rectal cancer (1 paper, 2022). A primary or metastatic malignant neoplasm that affects the rectum. "The intersection of the candidate target genes in the MAPK pathway and the overexpressed genes in colon and rectal cancer in TCGA and GTEx was taken, and 5 candidate genes EFNA2, RPS6KA2, MAPK13, EFNA3 and FGFR3 were identified." (PMID 34998382, 2022).
triple-negative breast carcinoma (1 paper, 2023). An invasive breast carcinoma which is negative for expression of estrogen receptor (ER), progesterone receptor (PR), and human epidermal growth factor receptor 2 (HER2). "Synthesized EFNA2-targeted immunoliposomes showed significant antitumor activity in NSCLC and triple-negative breast cancer xenograft models." (PMID 37570716, 2023).
viral infection (1 paper, 2023). "Among these factors, adult enhanced Efna2 showed a distinctive phenotype in controlling viral infection in bEnd.3 cells and primary BCECs and in viral plaque production." (PMID 37202395, 2023). "In our study, we observed direct treatment of BCECs with rec-EFNA2 reduced viral infection in vitro." (PMID 37202395, 2023). "For example, ephrinA2 (Efna2; an angiogenic molecule) and H2q6 (belonging to MHC class I family) were expressed at higher levels in adult microvessel fragments, regardless of virus infection." (PMID 37202395, 2023).
tumor (17 papers, 2006 to 2025). "The targeting of EPHA2, EPHA10, EPHB4, ephrin-A2, ephrin-A4, as well as ephrin-B2 in BC cells or xenograft models is associated with apoptosis induction, tumor regression, anticancer immune response activation, and impaired cell motility." (PMID 36499598, 2022). "We therefore developed a multimodal oncolytic herpes simplex virus (oHSV) that expresses ephrin A2 (EphA2), a shared tumor-associated antigen (TAA) expressed by many tumors to improve immune-mediated antitumor activity." (PMID 34599026, 2021). "Furthermore, targeting of EPHA10, EPHB4, ephrin-A2, and ephrin-A4, as well as ephrin-B2 in BC cells or xenograft models was associated with tumor regression, anticancer T-cell activation, and impaired cell motility." (PMID 36499598, 2022). "The only patient with a CNA other than deep deletion has amplification of EFNA2, a tumor of mixed histological subtype with numerous CNAs, and a pathogenic mutation of GNAQ." (PMID 41516312, 2025). "As a consequence, pathological stage, residual tumor, and the expression of EFNA2, EFNA3, and EFNA5 had significant prognostic significance in LUAD." (PMID 35945523, 2022). "EFNA2 was significantly upregulated in HCC cell lines and tissue samples, and its overexpression was associated with more aggressive tumor behaviors." (PMID 36052169, 2022). "The results indicated that EFNA2 expression correlated with tumor residue; the expression of EFNA3 and EFNA4 correlated with age; EFNA5 expression correlated with the number of pack-years smoked." (PMID 35945523, 2022). "In the tumor microenvironment, upregulation of ephrin-A2, ephrin-A3, EphB2, and EphB4, to name a few, on vascular cells in response to tumor factors has been the most well-studied." (PMID 31333644, 2019). "The first one was the Ephrin A2-BiTE-armed oncolytic vaccinia virus, which induced PBMCs activation and tumor cell cytotoxicity in vitro and in vivo." (PMID 30683154, 2019). "For example, some of the epialleles had large JSDs between tumor core and tumor periphery, but the differences of average methylation levels were small (such as epiallele chr19:1299820-1299851, in the exon of gene EFNA2; for C1 and P6, JSD=0.687, meth_C1=0.725, meth_P6=0.823)." (PMID 33754068, 2021). "Additionally, both forward and reverse IP experiments revealed no detectable interactions between EphA2 and EFNA2 or EFNA5, suggesting that other receptors and downstream pathways may mediate the tumor-suppressive roles of EFNA2 and EFNA5." (PMID 39964764, 2025). "This divergence is evident in our study, in which EFNA2 and EFNA5 overexpression reduced cell proliferation, migration, and tumor growth, in contrast to EFNA1’s tumor-promoting effects." (PMID 39964764, 2025). "In contrast, overexpression of either EFNA2 or EFNA5 significantly reduced cell proliferation and migration in vitro and tumor growth in vivo in comparison with control cells, suggesting divergent biological roles among ephrinA family members." (PMID 39964764, 2025). "In our study, EFNA2-EPHA interactions scored highly among the tumor-to-tumor and tumor-to-stroma signaling directions." (PMID 36676129, 2023). "We found that the expression of EFNA1, EFNA2, EFNA3, EFNA4, EFNB1, and EFNB2 was upregulated in the tumor tissues of most cancers compared with corresponding normal tissues." (PMID 36052169, 2022). "For example, BCL9L, P2RX6, RER1, EFNA2, CASK, CERCAM, and PTPRN were demonstrated to promote EMT, metastasis, and invasion of tumor cells." (PMID 35586092, 2022). "DNA methylation data showed that EFNA2 and EFNA3 positively correlated with tumor stemness in most cancers, whereas other family members revealed opposite results in various cancers." (PMID 35945523, 2022). "The expression levels of EphA3, A4, A5, A7, A8, B1 and B4 and of ephrin A2, A3, A4, B2 were relatively low in both normal and tumour samples and these genes were not considered further." (PMID 16737551, 2006).
tumor (continued). "Whereas EFNB3 showed low expression in cancerous tissues, EFNA2 and EFNA5 expression showed no evident difference between tumor and normal tissues." (PMID 36052169, 2022).
cancer (14 papers, 2008 to 2023). A tumor composed of atypical neoplastic, often pleomorphic cells that invade other tissues. "Efna2 has been recently established to have roles from neuronal development, differentiation and migration to angiogenesis and cancer metastasis." (PMID 37202395, 2023). "A positive correlation was noted between the expression of EFNA1, EFNA3, EFNA4, EFNA5 and CNV in most cancer types; however, EFNA2 expression was only weakly correlated with CNV." (PMID 35945523, 2022). "Cancer cells can differentiate and enhance EC-like characteristics by expressing VE-cadherin and ephrin A2." (PMID 36012949, 2022). "According to the previous data, Ephrin A2 mutant cancer cells demonstrated a decreased migration capacity, consequently resulting in a reduction in the number of metastasis in animal models." (PMID 33919252, 2021). "For example, EVs from senescent stromal cells can enhance the proliferation of cancer cells by promoting the activation of the ephrin-A2 tyrosine kinase receptor, which interacts with overexpressed ephrin-A1 on the surface of the cancer cells, thereby boosting an Erk-dependent proliferation pathway." (PMID 37445973, 2023). "Furthermore, we identified several RNA-binding proteins, including HuR, that interact with these clusters, and we show that EfnA2, EphA2, and EphA4 are direct posttranscriptional targets of HuR in cancer cell lines." (PMID 18648668, 2008). "The results showed that EFNA1 and EFNA4 had the highest expression in pan-cancer, followed by EFNA3 and EFNA5 with high expression, and EFNA2 with low expression." (PMID 35309935, 2022). "Based on RNA expression data, EFNA1 and EFNA5 were negatively correlated with the stem cell scores in most cancers, whereas EFNA2, EFNA3, and EFNA4 exhibited varying correlations with stem cell scores in different cancers." (PMID 35945523, 2022). "Upon examination of VE-cadherin, ephrin A2, VEGFR2, laminin 5γ2, MMP1, MMP2, MMP9 and MMP14 by the human cancer cells, we made the surprise finding that of the genes investigated, VE-cadherin (CDH5) was the most highly expressed." (PMID 32246008, 2020). "In the majority of cancers, EFNA1, EFNA2, EFNA3, and EFNA4 were suppressed by stromal and/or immune components, whereas EFNA5 demonstrated different trends in the stromal and immune scores across different cancers." (PMID 35945523, 2022). "Two additional genes known primarily for their contribution to angiogenesis, VEGFR2 (KDR) and Ephrin A2 (EPHA2), were lowly expressed by the human cancer cells and did not change in response to aspirin treatment." (PMID 32246008, 2020).
infection (5 papers, 2018 to 2025). The state of being infected such as from the introduction of a foreign agent such as serum, vaccine, antigenic substance or organism. "KHSV interacts with and activates Ephrin A2 early during infection, which in turn associates with phospho-c-Cbl, NM-IIA, as well as clathrin and its adapter protein AP2 to promote CME." (PMID 41217108, 2025). "These include B cell-mediated transfer, infection through cell-to-cell contact, and the direct infection of epithelial cells that express a recently identified viral receptor Ephrin A2." (PMID 33669217, 2021). "In this assay, the infection rate was quantified at 48 h post infection (p.i.)since human ephrin A2- and A5-mediated CedV entry could only be observed 48 h p.i., as has been reported." (PMID 40285015, 2025). "This included three receptor–RBP pairs for which mRNA levels were significantly associated with infection in the analyses (Cedar–EFNB1, Lujo–NRP2 and LCMV–DAG1), versus four with no apparent association (HCV–SCARB1, Cedar–EFNA2, SFTSV–MYH9 and rabies–NCAM1)." (PMID 39747691, 2025). "Similarly, infection with the Cedar virus pseudotype was positively associated with the expression of EFNB1 and EFNB2 (P < 0.01), but not of EFNA2 or EFNA5." (PMID 39747691, 2025).
neurological disease (1 paper, 2023). "Induction of Cx43 by 4-phenylbutyric acid (4-PBA) inhibited neurological disease in weanling mice, while Efna2 deficiency increased disease in adult mice." (PMID 37202395, 2023). "To examine whether Efna2 has a role in restricting LACV infection of the CNS in vivo, we analyzed the development of neurological disease in normally resistant adult mice deficient in Efna family members." (PMID 37202395, 2023). "Thus, we show that Efna2 and Cx43 expressed by BCECs are key mediators of LACV-induced neuroinvasion and neurological disease." (PMID 37202395, 2023).
EFNA2 also shares sentences with these, for which no sentence is quoted: cutaneous melanoma (2 papers); lung squamous cell carcinoma (2); acute myeloid leukemia (1); Anxiety (1); astrocytoma (1); breast invasive carcinoma (1); cervical carcinoma (1); colon adenocarcinoma (1); esophageal carcinoma (1); kidney (1); lung adenocarcinoma (1); melanoma (1); multiple sclerosis (1); nasopharyngeal carcinoma (1); ovarian serous cystadenocarcinoma (1); pancreatic adenocarcinoma (1); prostate adenocarcinoma (1); uterine corpus endometrial carcinoma (1).